TRIM24 (tripartite motif containing 24)
Diseases named in the same sentence as TRIM24 in open-access papers (continued):
Sharing a sentence is not in itself a finding about the gene and the disease.
glioma (continued). "The expression of miR-138-2-3p, TRIM24 and β-catenin in glioma and normal brain tissues was measured using RT-qPCR and western blot analysis." (PMID 32293515, 2020). "It was shown that miR-138-2-3p was lowly expressed, while the mRNA and protein expression of TRIM24 was elevated in glioma tissues (all p < 0.05)." (PMID 32293515, 2020). "To further assess which genes are co-upregulated by EGFR and TRIM24 in glioma cells, we identified 35 genes that were significantly reduced by TRIM24 knockdown and upregulated by EGFRvIII in LN229 GBM cells (fold change >2, p < 0.05)." (PMID 29129908, 2017). "In multiple glioma cell lines and patient-derived glioma stem cells (GSCs), EGFR signaling promotes H3K23 acetylation and association with TRIM24." (PMID 29129908, 2017). "Collectively, these findings suggest that TRIM24 plays an important role in EGFR/EGFRvIII-driven tumorigenesis in gliomas." (PMID 29129908, 2017). "The newly established roles of TRIM24 and H3K23ac in tumorigenesis provide a strong rationale for targeting them to treat glioma patients with high EGFR and STAT3 signaling activity." (PMID 29129908, 2017). "Our analyses of clinical gliomas reveal a close correlation between co-expression of TRIM24/p-EGFR, TRIM24/H3K23ac and TRIM24/p-STAT3 with poor prognoses in GBM patients." (PMID 29129908, 2017). "Collectively, these findings suggest that H3K23ac/TRIM24/STAT3 signal pathway plays an important role in EGFR/EGFRvIII-driven tumorigenesis in human gliomas." (PMID 29129908, 2017). "TRIM24 is elevated in gliomas and positively correlates with tumor malignancy." (PMID 39160596, 2024). "But the prognostic role of TRIM24 in glioma has yet to be investigated." (PMID 37367937, 2023). "NCK1-AS1 by modulating the miR-137/TRIM24 axis could increase the resistance of glioma cells to TMZ." (PMID 34178658, 2021). "This STAT3/TRIM24/ID1 axis mediates glioma stem cell proliferation and self-renewal." (PMID 33810347, 2021). "Herein, we speculated that NCK1-AS1 might regulate TRIM24 expression via sponging miR-138-2-3p and further regulate the Wnt/β-catenin pathway in glioma." (PMID 32293515, 2020). "Silencing of NCK1-AS1 might inhibit the proliferation, invasion, migration and resistance to death of glioma cells, and inhibit the metastasis of tumor in vivo through down-regulating TRIM24 and the following Wnt/β-catenin inactivation." (PMID 32293515, 2020). "The TRIM24 gene has been shown to be targeted by NCK1‐AS1 in glioma cells." (PMID 32677374, 2020). "Moreover, our study identified that inhibited miR-138-2-3p or promoted TRIM24 stimulated Wnt/β-catenin activation in glioma cells, which was in line with the previous studies." (PMID 32293515, 2020). "It is known that KAT6A promotes the binding of H3K23ac to TRIM24 in glioma cells." (PMID 32677374, 2020). "Thus, this study provides clinical and mechanistic evidence demonstrating that H3K23ac/TRIM24 is critical for EGFR-driven tumorigenesis in human gliomas." (PMID 29129908, 2017). "Taken together, our data suggest that TRIM24 is a co-activator of STAT3 in gliomas." (PMID 29129908, 2017). "We identify TRIM24 as an oncogene in gliomas, consistent with previous reports." (PMID 29129908, 2017). "To test whether TRIM24 is critical for EGFRvIII-driven glioma tumorigenesis, we knocked down TRIM24 in LN229/EGFRvIII and U87/EGFRvIII cells using two separate shRNAs." (PMID 29129908, 2017). "To understand why TRIM24 is important for EGFR/EGFRvIII-driven glioma tumorigenesis, we performed transcriptome analysis in LN229 parental (LN229/P) and LN229/EGFRvIII (LN229/vIII) GBM cells transfected with an empty vector or TRIM24 shRNAs (LN229/vIII/shT24-1 and LN229/vIII/shT24-2) using RNA-seq." (PMID 29129908, 2017).
glioma (continued). "As the detection of a recurrent TRIM24::MET fusion expands the spectrum of known driving fusion genes in infant-type hemispheric glioma, this comparative illustration may indicate a notable clinico-pathological heterogeneity of tumors bearing this particular molecular driver alteration." (PMID 38902810, 2024). "We assumed that NCK1-AS1 could affect glioma progression through the miR-138-2-3p/TRIM24 network and the following Wnt/β-catenin pathway, with gain- and loss-of functions of these molecules performed in both cell and animal experiments to validate this hypothesis." (PMID 32293515, 2020). "To further determine whether TRIM24 is critical for glioma tumorigenesis, we analyzed the effects of TRIM24 on patient-derived glioma stem cells (GSCs) using established methods to evaluate cell signaling pathways, self-renewal, proliferation, and tumor forming ability." (PMID 29129908, 2017). "In glioma, KAT6A activates phosphatidylinositol-4,5-bisphosphate 3-kinase catalytic subunit alpha (PIK3CA) transcription by recruiting tripartite motif-containing 24 (TRIM24), thereby promoting tumorigenesis." (PMID 40475780, 2025). "In glioma cells, PVT1 recruits COPS5 to deubiquitinate and stabilize TRIM24, leading to the activation of STAT3 signaling and the induction of malignant biological behaviors." (PMID 39160596, 2024). "Taken together, our data suggests that the epigenetic regulator TRIM24 can function as a driver of Ep‐GBM‐like tumors transformation and a regulator of glioma progression." (PMID 38828688, 2024). "Higher TRIM24 expression was correlated with poor OS, DSS, PFI, in all of the patients with glioma with significance." (PMID 37367937, 2023). "Our study suggests that TRIM24, IDH1, LBR, HMG20B, USP49 and RCC1 were all highly expressed in glioma tissues and gliomar cell lines both at the mRNA and protein level." (PMID 36246611, 2022). "TRIM24, TRIM47, TRIM44, TRIM31, TRIM14, TRIM21, and TRIM28 have exhibited significant prognostic value regarding OS and/or PFS of glioma patients." (PMID 36139694, 2022). "The RT-qPCR assay showed that the six signature genes (TRIM24, IDH1, LBR, HMG20B, USP49, and RCC1) were up-regulated in glioma cell lines in mRNA expression level." (PMID 36246611, 2022). "The potential intersect genes were further compared with the highly expressed genes in the glioma microarrays GSE50161 and GSE35493, after which 2 intersections TRIM24 and GLISE were found." (PMID 32293515, 2020). "TRIM24 is upregulated by EGFR activation, and is required for EGFR-driven glioma cell proliferation, cell migration, colony formation in soft agar, orthotopic xenograft tumor growth in mouse brain." (PMID 29129908, 2017). "We show that TRIM24 is upregulated and amplified in GBM specimens, and its expression is correlated with glioma progression." (PMID 29129908, 2017). "Taken together, these data support the role of EGFR/H3K23ac/TRIM24/STAT3 signaling in the pathophysiology, clinical progression, and aggressiveness of human gliomas." (PMID 29129908, 2017). "Notably, in gliomas, the aberrantly expressed TRIM24 recruits DNA-PKcs and PHAX, leading to TRIM24 phosphorylation and subsequent oncogenic transcriptome alterations." (PMID 40940882, 2025). "Therefore, we analyzed the potential target miRNAs of NCK1-AS1 and the following genes via integrated online bioinformation system, glioma microarrays, dual luciferase reporter gene, RNA pull-down and RIP assays, after which we identified the interactions among NCK1-AS1, miR-138-2-3p and TRIM24." (PMID 32293515, 2020).
glioma (continued). "Moreover, Kaplan-Meier analyses of survival showed that high expression levels of p-EGFR but not TRIM24 could serve as a predictor of a worse prognosis for patients with gliomas." (PMID 29129908, 2017).
glioblastoma (15 papers, 2016 to 2025). The most malignant astrocytic tumor (WHO grade IV). "The first was based on the observation of KAT6A-induced TRIM24-mediated PIK3CA mRNA expression in glioblastoma." (PMID 40676628, 2025). "Although in glioblastoma, KAT6A controls PIK3CA gene expression through TRIM24 binding to this gene promoter, in this study, TRIM24 promoted cell survival by associating to PI3Kα protein, thereby increasing its stability." (PMID 40676628, 2025). "TRIM24 emerges as an oncogenic transcriptional co-activator in epidermal growth factor receptor (EGFR)-driven glioblastoma." (PMID 39160596, 2024). "Recent research unveiled that TRIM24 upregulated in glioblastoma, and it accelerated tumor growth and induced chemotherapy resistance via the phosphatidylinositide 3-kinase (PI3K)/Akt pathway." (PMID 35105347, 2022). "TRIM24 was reported to promote the stemness and invasiveness of glioblastoma cells via activating the pluripotency transcription factor Sox2 expression." (PMID 35205738, 2022). "TRIM24 has also been found to mediate chemoresistance in gastric cancer and glioblastoma." (PMID 40097385, 2025). "The knockdown of TRIM24 reduced glioblastoma stem cell self-renewal and invasive growth." (PMID 35205738, 2022). "Since TRIM24 has also been described as a co-activator of STAT3 in glioblastoma, it cannot be excluded that a similar mechanism may also account for chemoresistance by TRIM24 in CRC." (PMID 33066016, 2020). "In glioblastoma, KAT6A expression increases PI3Kα levels through the binding of TRIM24 to H3K23Ac in the PIK3CA gene promoter." (PMID 40676628, 2025). "It’s also reported that TRIM24 activated the expression of SOX2, thereby governing the stemness and invasion of glioblastoma both in vitro and in vivo." (PMID 39160596, 2024). "TRIM24, through PI3K/AKT/NF-κB signaling, controls the expression of the DNA repair enzyme O6-methylguanine-DNA methyltransferase (MGMT), contributing to increased resistance to temozolomide, the standard chemotherapeutic agent for glioblastoma." (PMID 39160596, 2024). "TRIM24, which contains both a PHD- and a bromodomain interacting with the dual histone mark H3K4me0/H3K23Ac, is an oncogenic transcriptional coactivator overexpressed in breast and prostate adenocarcinoma, along with glioblastoma, in which TRIM24 is a Stat3 coactivator." (PMID 35326630, 2022).
lung carcinoma (14 papers, 2011 to 2025). "Furthermore, TRIM24 overexpression was associated with high levels of cyclin D1 and p-Rb in lung cancer specimens." (PMID 22666376, 2012). "In addition, we also explored the association of TRIM24 with proliferation and invasion ability in several lung cancer cell lines." (PMID 22666376, 2012). "The protein expression of TRIM24 in primary lung cancer and its relationship with clinicopathological factors have not yet been examined." (PMID 22666376, 2012). "In conclusion, the present study investigated the expression pattern and clinicopathological significance of TRIM24 in NSCLC and addressed the biological role and potential mechanism of TRIM24 in lung cancer progression." (PMID 22666376, 2012). "Together, these results suggest that inhibiting TRIM24 expression induces cell cycle arrest at the G1-S transition and suppresses lung cancer cell growth." (PMID 22666376, 2012). "To validate the potential role of TRIM24 in lung cancer development, we first checked its expression level in several cell lines and picked up A549 and H1299 with relatively high TRIM24 level for further study." (PMID 22666376, 2012). "In this study, we demonstrated that TRIM24 protein expression in lung cancer tissues was higher than that in corresponding normal lung tissues." (PMID 22666376, 2012). "In order to explore the biological function of TRIM24 in lung cancer, we employed siRNA to knockdown TRIM24 expression in both H1299 and A549 cell lines." (PMID 22666376, 2012). "TRIM24 was found to be overexpressed in 81 of 113 (71.7%) human lung cancer samples and correlated with p-TNM stage (p = 0.0006), poor differentiation (p = 0.004), Ki67 index (p<0.0001), cyclin D1(p = 0.0096) and p-Rb expression (p = 0.0318)." (PMID 22666376, 2012). "Expression of TRIM24 was analyzed by western blot in a panel of lung cancer cell lines." (PMID 22666376, 2012). "Our study found a correlation between TRIM24 overexpression and pTNM stage and poor differentiation in lung cancer, which was in accord with previous data, suggesting TRIM24 may play an important role in lung cancer progression." (PMID 22666376, 2012). "So TRIM24 knockdown inhibited G1 to S transition in cell cycle progression, which might explain the mechanism of TRIM24 on lung cancer cell proliferation." (PMID 22666376, 2012). "In addition, the biological roles of TRIM24 in lung cancer cells are still unclear." (PMID 22666376, 2012). "Thus, our study suggested that TRIM24 functioned as an oncogene in lung cancer development." (PMID 22666376, 2012). "Similarly, the BRAF gene has been found translocated with TRIM4 in lung cancer and TRIM24 in both melanoma and lung cancer and the FGFR1 gene is translocated with TRIM24 in myeloproliferative syndrome." (PMID 32226386, 2020). "The E3 ubiquitin ligase RFWD3 binds the exonuclease TREX1 and protects it from TRIM24‐mediated ubiquitination and degradation, leading to the eradication of intracellular dsDNA, inhibition of the cGAS‐STING pathway, and immunosuppressive microenvironment of lung cancer." (PMID 41117130, 2025). "However, the expression pattern of TRIM24 as well as its correlation with clinical and pathological factors has not yet been defined in human lung cancer." (PMID 22666376, 2012).
gastric cancer (11 papers, 2015 to 2025). A primary or metastatic malignant neoplasm involving the stomach. "Despite the well-defined outcome of TRIM24 overexpression in cancers, the mechanism underlying its upregulation in gastric cancer remains completely unknown." (PMID 28114950, 2017). "TRIM24 was found to bind to the promoter region of Cyclin D1 utilizing ChIP analysis, offering partial clarification of the molecular mechanism underlying its impact on cell proliferation through transcriptional regulation of genes, which is consistent with the findings in gastric cancer cells." (PMID 39160596, 2024). "We are the first to demonstrate that TRIM24 promotes gastric cancer progression through the degradation of NRBP1, a tumor suppressor protein." (PMID 41430038, 2025). "Overexpression of miR-511 in MGC803 and HGC-27 cells resulted in the downregulation of TRIM24 expression, thus suppressing the Wnt/β-catenin pathway and inhibiting gastric cancer progression." (PMID 39768197, 2024). "In gastric cancer cells, overexpression of TRIM24 alters cell survival in response to 5-Fluorouracil (5-FU) treatment, indicating a potential role in chemoresistance." (PMID 39160596, 2024). "TRIM24 was overexpressed in gastric cancer tissues and cell lines (MGC803 and HGC-27), with a positive correlation observed between the mRNA levels of TRIM24 and β-catenin." (PMID 39768197, 2024). "In gastric cancer cells, TRIM24 promotes cell growth and induces chemotherapy resistance in an Akt dependent manner." (PMID 35105347, 2022). "However, in GC, investigations have primarily focused on surface phenomena such as Cyclin D1, AKT, and the Wnt/β-catenin signaling pathway, while deeper mechanistic insights into TRIM24’s role in gastric cancer remain inadequately explored." (PMID 41430038, 2025). "This discovery provides new mechanistic insights into how TRIM24 exerts its oncogenic effects and suggests that targeting TRIM24 or enhancing NRBP1 expression could serve as promising therapeutic strategies for the treatment of gastric cancer." (PMID 41430038, 2025). "Additionally, in gastric cancer, miR-511 had a decreased expression level in human gastric cancer tissues and cell lines (MGC803 and HGC-27), which was negatively associated with TRIM24." (PMID 39768197, 2024). "Our results provide the new evidence supporting the tumor-suppressive role of miR-511 in GC by suppressing TRIM24, suggesting that this novel miR-511/TRIM24 axis is critical in the control of gastric cancer tumorigenesis." (PMID 28114950, 2017). "Consistently, TRIM24-induced chemoresistance to 5-FU can be reversed by the AKT inhibitor LY294002, suggesting a regulatory relationship between TRIM24 and AKT signaling, resulting in chemotherapy in gastric cancer cells." (PMID 39160596, 2024). "Additionally, TRIM24 can promote NRBP1 ubiquitination at the K430 residue, subsequently leading to its degradation, ultimately inhibiting apoptosis in gastric cancer cells." (PMID 41430038, 2025). "TRIM24 showed enhanced expression in GC cells and gastric carcinoma tissue samples in comparison with gastric noncancerous tissues." (PMID 41430038, 2025). "Studies in various cancers, including HCC, gastric cancer, ovarian cancer, renal cell carcinoma, colorectal cancer, and NSCLC, have demonstrated that down-regulation of TRIM24 reduces the migratory and invasive capabilities of cancer cells and influences the expression of EMT-related proteins." (PMID 39160596, 2024). "Increasing evidence highlights the important roles of tripartite motif containing 24 (TRIM24) in tumor initiation and malignant progression in many tumors, including gastric cancer (GC)." (PMID 28114950, 2017).